HPSE (heparanase)
Diseases named in the same sentence as HPSE in open-access papers (continued):
Sharing a sentence is not in itself a finding about the gene and the disease.
cancer (295 papers, 2002 to 2026). A tumor composed of atypical neoplastic, often pleomorphic cells that invade other tissues. "Heparanase-2 (Hpa2), a homolog of heparanase that lacks heparan sulfate-degrading activity, is clinically associated with favorable cancer outcomes, but its role in pancreatic homeostasis remains poorly defined." (PMID 42212319, 2026). "Since the elevation of HPSE expression in cancer is often associated with more aggressive disease and poor prognosis, this has encouraged the development of HPSE inhibitors." (PMID 37508554, 2023). "Armoring CAR T-cells with ECM-degrading agents like heparanase or fibroblast activation protein to overcome the physical barriers posed by cancer-associated fibroblasts (CAFs) and ECM components." (PMID 37020537, 2023). "The causal involvement of heparanase in cancer metastasis has long been demonstrated in various types of cancer." (PMID 34199150, 2021). "Heparanase has been implicated in various pathological conditions, in particular cancer and inflammatory diseases." (PMID 33971986, 2021). "Heparanase (HPSE) gene single nucleotide polymorphisms (SNPs) have been found to be correlated with different human cancers." (PMID 33411145, 2021). "Heparanase is known to enhance the progression of many cancer types and is associated with a poor prognosis." (PMID 34050190, 2021). "HPSE expression is increased in different cancers and is associated with aggressive disease and poor prognosis." (PMID 32075104, 2020). "HPSE expressed by cancer cells promotes a number of key hallmark features such as proliferation, inflammation, invasion and metastasis and angiogenesis." (PMID 33256730, 2020). "Heparanase is also known to be expressed in many types of malignant tumors, and is associated with metastasis and angiogenesis." (PMID 32471161, 2020). "Further studies in endothelial cells showed that fatty acids caused the nuclear translocation of HPSE, leading to the regulation of genes related to glycolysis and the accumulation of lactate, a vital fuel source and regulator in cancer progression." (PMID 33256730, 2020). "Activation of these cancer stem cell regulators suggests stem cells are initiated by increased heparanase coupled with the loss of PTEN." (PMID 32899927, 2020). "Various studies have investigated the underlying mechanism for heparanase activity in cancer, including enhancement of angiogenesis and promotion of apoptosis and autophagy." (PMID 32471161, 2020). "Various studies have evaluated the genetic frequencies of HPSE polymorphisms in different cancers and diseases." (PMID 32869952, 2020). "The degradation of endogenous heparin by heparanase seems to play a major role in cancer-associated thrombosis." (PMID 32121387, 2020). "Heparanase expression is elevated in many types of tumors and is associated with more aggressive cancer and a poor prognosis." (PMID 32471161, 2020). "Heparanase has been implicated in many pathological conditions, especially inflammation and cancer, attributed to its degradation of heparan sulfate, a crucial component maintaining the integrity of the extracellular matrix." (PMID 31044520, 2019). "These and other results indicate that heparanase is causally involved in cancer progression and hence is a valid target for anti-cancer drug development." (PMID 29464068, 2018). "Clinically, elevated heparanase levels are most often associated with increased angiogenesis and metastasis, and reduced postoperative survival of cancer patients." (PMID 29721203, 2018). "Expression and activity of heparanase, an endoglycosidase that cleaves heparan sulfate (HS) side chains of proteoglycans, is associated with progression and poor prognosis of many cancers which makes it an attractive drug target in cancer therapeutics." (PMID 28359266, 2017). "Heparanase has been implicated in several normal and pathological processes, including cancer metastasis and angiogenesis, the regulation of food intake, and metabolism." (PMID 29066725, 2017).
cancer (continued). "Heparanase activity is involved in cancer growth and development in humans andsingle nucleotide polymorphisms (SNPs) in the heparanase gene(HPSE) have been shown to be associated with tumors." (PMID 28981558, 2017). "Heparanase is strongly implicated in cancer metastasis and neovascularization and is up-regulated in essentially all human tumors examined." (PMID 24465803, 2014). "A less-known way of regulation of this process is through heparanase enzyme, an endoglycosidase, implicated in cancer progression and metastasis." (PMID 25309924, 2014). "Osteopontin (OPN) and CA125 have similarly been related to cancer-linked heparanase activity in addition to hyaluronan, TRA and ferritin." (PMID 23516416, 2013). "Heparanase, an enzyme that cleaves heparan sulfate, which is upregulated in many cancers and is associated with enhanced tumor growth, was shown to dramatically increase exosome secretion in several human cancer cell lines." (PMID 23839094, 2013). "Heparanase is strongly associated with cancer progression and metastasis, including cell survival, invasion, proliferation, neovascularization, and the creation of a growth-permissive microenvironment and it has both prognostic and therapeutic applications." (PMID 22276173, 2012). "A mechanism rather than genetic and epigenetic regulation underlines the TGS of heparanase induced by TSS-targeted siRNA in human cancer cells." (PMID 22363633, 2012). "A long-term research on the biology of heparanase led to the cloning of a single gene encoding a HS-degrading endoglycosidase (heparanase) which plays important roles in cancer metastasis, angiogenesis and inflammation." (PMID 20419162, 2010). "Numerous studies emphasize the involvement of MMPs and heparanase in disease situations associated with cancer metastasis, angiogenesis and inflammation." (PMID 19360105, 2009). "Previous studies implicated heparanase in various normal and pathological processes ranging from bone remodelling, hair growth and kidney function to cancer metastasis, inflammation and angiogenesis." (PMID 19360105, 2009). "Its functional activity can be modulated by heparanase, an enzyme that cleaves heparan sulfate chains and whose expression has been associated with an aggressive phenotype in many cancers." (PMID 19305494, 2009). "Heparanase activity has been traditionally correlated with cell invasion associated with cancer metastasis, a consequence of structural modification that loosens the ECM barrier." (PMID 18545691, 2008). "It is possible that higher heparanase levels and procoagulant activity found in shift workers may contribute to an increase in inflammatory markers and possibly, the enhanced risk of cancer." (PMID 39859197, 2025). "HPSE has been implicated in several inflammation-driven cancers (see “Inflammation in cancer”)." (PMID 41301515, 2025). "Dysregulated HPSE expression or activity has been implicated in various pathological conditions, including fibrosis, chronic inflammation, cancer progression, angiogenesis, metastasis, and immune evasion, positioning this enzyme as a pivotal driver of ECM plasticity in both health and disease." (PMID 41301515, 2025). "Importantly, heparanase knockout (KO) mice exhibit no obvious immunological and other deficits, implying that inhibition of heparanase will cause minimal side effects in cancer patients." (PMID 37547889, 2023). "Other mediators released by cancer cells that can cause platelet activation include, firstly, cancer pro-coagulant, a protease that activates factor X independently of TF, and secondly, the enzyme heparanase, which is found in platelets and enhances TF activity." (PMID 37569299, 2023). "We examined whether sulfated hyaluronan exerts inhibitory effects on enzymatic and biological actions of heparanase, a sole endo-beta-glucuronidase implicated in cancer malignancy and inflammation." (PMID 35563446, 2022).
cancer (continued). "Chromatin immunoprecipitation experiments revealed that heparanase is recruited to promoters and 5′ coding regions of microRNA genes miR-9 and miR-183 (previously implicated in cancer and epithelial-mesenchymal transition (EMT)) and other genes linked to development and differentiation pathways." (PMID 34681753, 2021). "The HPSE gene encodes heparanase (HPSE), a key player in cancer, inflammation, and autoimmunity." (PMID 34685503, 2021). "Moreover, heparanase levels correlate with shorter postoperative survival of cancer patients altogether indicating that heparanase is causally involved in cancer progression, encouraging the development of heparanase inhibitors as anti-cancer drugs." (PMID 34199150, 2021). "Thus, overexpression of heparanase leads to a loss of extracellular matrix integrity, enabling invasion, and the dissemination of cancer cells." (PMID 34070058, 2021). "HPSE has been implicated in a number of inflammation-driven cancers." (PMID 33256730, 2020). "Additionally, this review will also explore the complexities associated with utilising HPSE as an anti-cancer therapeutic target, considering its role in both physiological and pathological settings." (PMID 33256730, 2020). "Heparanase cleaves the extracellular matrix by degrading heparan sulfate that ultimately leads to cell invasion and metastasis; a condition that causes high mortality among cancer patients." (PMID 32132875, 2020). "Finally, both HPSE and Sdc-1 regulate the activity of pathways relevant to cancer progression, such as the stemness-associated Wnt pathway and metastasis-related focal adhesion kinase (FAK) signaling." (PMID 32477959, 2020). "Thus, the T5 variant of heparanase displays many of the biological effects of the full-length protein, at least in the cancer models studied to date, yet it lacks enzymatic activity." (PMID 31850210, 2019). "The upregulation of HPSE has been implicated in many types of cancers, including CRC." (PMID 31001480, 2019). "Upregulation of heparanase occurs in essentially all human tumors and is closely correlated with an invasive phenotype in experimental models and has been linked to worse outcomes in cancer patients." (PMID 32010611, 2019). "Looking forward, it is important to keep in mind that several cancers are induced by viruses and, thus, the same HPSE inhibitors may represent a useful tool to fight viral infection and associated cancer." (PMID 30487472, 2018). "Heparanase is an endoglycosidase that cleaves heparan sulfate (HS) side chains of HS sulfate proteoglycans into shorter oligosaccharides, activity that is highly implicated in cellular invasion associated with cancer metastasis and inflammation." (PMID 28386074, 2017). "Heparanase was readily detected in most metastases, and in stage IVc patients was associated with poor survival rates, suggesting that heparanase plays an important role in the progression of established metastatic lesions and, thus, is a promising target for the development of anti-cancer drugs." (PMID 27732945, 2016). "Notably, heparanase is elevated in a number of human pathological tissues, e.g. cancer and its activity is implicated in neovascularization, inflammation, and autoimmunity." (PMID 27129145, 2016). "Heparanase cleaves enzymatically heparin sulfate and with serine proteinases and metalloproteinases plays a crucial role in the extracellular matrix remodeling associated both with in situ tumors growth and the metastatis-related invasion of cancer cells." (PMID 23516416, 2013). "Thus, heparanase represents a potential tumor associated antigen (TAA) that could be exploited across multiple cancer types." (PMID 31110966, 2019). "Heparanase expression has been linked to tumorigenesis in a number of different cancers, for example, acute myeloid leukaemia, bladder, brain, breast, colon, gastric, oesophageal, oral, pancreatic, and cervical cancer, suggesting that it may be a suitable target for drug therapy." (PMID 25295847, 2014).
cancer (continued). "Materials and methods: Human cancer cell lines were exposed to exogenous heparanase or transfected with either a vector enhancing heparanase expression (heparanase-high), a control vector (heparanase-low) or a vector containing a mutated enzymatically inactive form of heparanase." (PMID 26082317, 2013). "The biological features of markers such as heparanase emphasize the importance to design cost effective methods allowing the early detection of such biomarkers in serum and tissues both for diagnostic and prognostic purposes as well as for monitoring cancer treatments." (PMID 23516416, 2013). "Heparanase expression has been linked to tumorigenesis in a number of different cancers, for example, acute myeloid leukaemia, bladder, brain, breast, colon, gastric, oesophageal, oral, and pancreatic, suggesting that it may be a suitable target for drug therapy." (PMID 22719856, 2012). "Heparanase is an endo-β-D-glucuronidase that cleaves heparan sulfate (HS) side chains at a limited number of sites, activity that is strongly implicated with cell invasion associated with cancer metastasis, a consequence of structural modification that loosens the extracellular matrix barrier." (PMID 23908791, 2011). "This heparanase expression is upregulated in astrocytes by nerve growth factor (NGF) in response to factors secreted by cancer cells, including TGF-β1, IL-1β, and bFGF." (PMID 41268299, 2025). "Cancer cells show altered HS patterns and increased heparanase production, particularly affecting growth factor pathways like FGF, VEGF, and PDGF." (PMID 40143176, 2025). "We characterized the interaction of this mAb with the heparanase protein and demonstrated its efficacy in preclinical models of cancer, administered alone and in combination with conventional anti-cancer drugs." (PMID 40940793, 2025). "Several mechanisms were proposed for suramin’s anti-cancer activity, among which its anti-heparanase activity is gaining a great deal of interest." (PMID 40723905, 2025). "NAC heparins can also preserve bone morphogenetic protein-2 bioactivity and inhibit cancer progression by interfering with heparanase activity and selectin-mediated interactions." (PMID 40143176, 2025). "Heparanase 1 (HPSE1) is a unique endoglycosidase responsible for the enzymatic cleavage of heparan sulfate, thereby playing important functions in cancer processes." (PMID 40899692, 2025). "Heparanase, the primary enzyme responsible for the degradation of intercellular heparan sulfate, is markedly upregulated in malignant tumors." (PMID 40904706, 2025). "During the invasion of cancer cells in the brain, astrocyte cells facilitate this process by releasing heparanase, an enzyme that breaks down heparan sulfate proteoglycans in the extracellular matrix." (PMID 41268299, 2025). "The role of HPSE in cancer largely derives from its capacity to modulate cellular responses across multiple levels, influencing oncogenic signaling, proliferation, and growth factor activity." (PMID 41301515, 2025). "Heparin has previously been shown to function as a heparanase inhibitor, but due to undesirable anti-coagulant properties in cancer treatments, other heparin mimetics have been explored as heparanase inhibitors." (PMID 40723905, 2025). "Heparanase inhibition is a potential target for cancer therapeutics since the action of heparanase leads to the degradation of the extracellular matrix and the release of angiogenic growth factors." (PMID 40723905, 2025). "Heparanase inhibitors have been developed as potential anti-cancer agents, and clinical trials are currently underway to evaluate their efficacy." (PMID 39202399, 2024). "Mast cell heparanase activity is essential for estrogen receptor up-regulation and stem-like properties of cancer cells." (PMID 39349458, 2024). "Most malignant tumors express heparanase, including prostate, lung, breast, colon, and kidney cancers." (PMID 39202399, 2024).
cancer (continued). "Unlike the intense research effort devoted to exploring the significance of heparanase in cancer, very little attention was given to Hpa2, a close homolog of heparanase." (PMID 38519456, 2024). "One notable target in cancer therapy is heparanase, an endoglycosidase prevalent in malignant tumors." (PMID 39459002, 2024). "Heparanase inhibitors have been shown to slow disease progression in cancer studies; the most promising and potent inhibitor in clinical trials is PG545, a polysulfated oligosaccharide-cholestanyl aglycone." (PMID 38302978, 2024). "Heparanase expression has been reported in various cell types, including leukocytes, endothelial cells, and cancer cells." (PMID 39202399, 2024). "Heparanase is upregulated during the progression of most cancers and via its enzyme activity promotes extracellular matrix degradation, angiogenesis and cell migration." (PMID 37091070, 2023). "Based on these findings, heparanase inhibitors are developed for treatment of cancers and inflammatory diseases." (PMID 36980232, 2023). "Accordingly, inhibition of cancer cell invasion by heparanase blockade was further confirmed in pediatric brain tumor cells in vitro." (PMID 37728789, 2023). "Over four decades of research have cemented the key role of HPSE in malignant disease progression and it has emerged as an attractive but challenging anti-cancer therapeutic target." (PMID 37297024, 2023). "This nanomolar, mechanism‐based, irreversible heparanase inhibitor markedly reduced cancer aggression in in cellulo and in vivo cancer models." (PMID 37547889, 2023). "To date, in vivo models for studying the role of HPSE in cancer have focused on using transgenic HPSE-overexpressing mice and immunodeficient mice." (PMID 37297024, 2023). "Heparanase inhibitors have also been developed as drugs and vaccines to be used in cancer treatment." (PMID 37759706, 2023). "Heparin-like compounds that inhibit heparanase activity are being evaluated in clinical trials for various types of cancer." (PMID 36980232, 2023). "Apart from its role in cancer outcomes described in cancer-related studies, heparanase has also been found to play a significant role in modulating inflammatory responses." (PMID 36980232, 2023). "To examine this possibility we treated wt and Hpa2-KO female mice with the heparanase inhibitor Roneparstat (SST0001) which was evaluated clinically in cancer patients." (PMID 37491420, 2023). "It appears that the heparanase/Hpa2 ratio impacts tissue hemostasis and the balance between cancer progression and suppression." (PMID 36980254, 2023). "Heparanase expression is found to be elevated in almost all cancers examined including various carcinomas, sarcomas, and hematological malignancies." (PMID 36980232, 2023). "Heparin, a sulfated glycosamynoglycan, being the closest mimic of HS, has been initially considered as a putative heparanase-1 inhibitor, but its strong anticoagulant activity limits its use as an anti-cancer treatment." (PMID 36680276, 2023). "This review addresses the perspectives of using heparanase inhibitors, not only for cancer treatment, but also as antivirals." (PMID 36680276, 2023). "Unlike the intense research effort devoted to exploring the significance of heparanase in cancer progression, very little attention was given to Hpa2." (PMID 37491420, 2023). "These include benzoxazoles, benzoimidazoles, HS-configured pseudodisaccharides, and heparanase-neutralizing antibodies, all of which showed specific anti-heparanase-1 and anti-cancer activity in vitro in nanomolar concentrations." (PMID 36680276, 2023). "Together it appears that nuclear heparanase promotes chromatin remodeling that opens its conformation allowing access to promotors of genes that affect cancer progression." (PMID 37547889, 2023).